ARL8B (ARF like GTPase 8B)
Diseases named in the same sentence as ARL8B in open-access papers:
ARL8B is named in the same sentence as 23 diseases in open-access papers, as found by Europe PMC text mining. Sharing a sentence is not in itself a finding about the gene and the disease. The quoted sentences say what the papers report.
breast carcinoma (7 papers, 2016 to 2024). "In the context of breast cancer, high expression of ARL8B or BORC subunit genes is associated with poor prognosis, and expression of these proteins promotes invasion of cells that evade radiation treatment." (PMID 39016685, 2024). "Consistent with this, we found that a more peripheral distribution of lysosomes regulated by Arl8b-BORC-subunits was associated with enhanced invasiveness in breast cancer cells." (PMID 33110168, 2020). "Similarly, ADP ribosylation factor like GTPase 8B (ARL8B) is thought to play a crucial role in cancer cell invasion, with high levels of expression associated with poor prognosis in patients with breast cancer." (PMID 39217195, 2024). "The overexpression of the ARL8B gene is significantly accompanied by the poor prognosis of breast cancer patients, contradicting the notion that ARL8B is a protective factor." (PMID 38586328, 2024). "ARL8B is a pivotal regulative gene of lysosomal location; a prior study demonstrated that the expression of ARL8B is closely correlated with the prognosis of breast cancer patients." (PMID 34194501, 2021). "To further verify the role of Arl8b in the enhanced invasion of IR-S cells, we generated breast cancer cell lines in which Arl8b was knocked down by shRNAs." (PMID 33110168, 2020). "To determine which subunits of BORC cooperate with Arl8b in cancer progression and invasion, we analyzed a breast cancer dataset available at The Cancer Genome Atlas (TCGA)." (PMID 33110168, 2020). "We also showed that Arl8b silencing suppressed the enhanced invasion of IR-S breast cancer cells in vitro and tumor metastasis in vivo." (PMID 33110168, 2020). "We also generated Arl8b KD in MDA MB 231 human breast cancer cells and confirmed Arl8b KD prevents acidic pHe-mediated anterograde lysosome trafficking in breast cancer cells as well." (PMID 27105540, 2016). "High expression of both the ARL8B and BLOC1S2 genes, the latter of which is a BORC-subunit, was associated with poor survival rates in breast cancer patients and increased lymph node metastasis, both of which could account for the increased invasiveness." (PMID 33110168, 2020). "Furthermore, the knockdown of Arl8b prevented the enhanced invasiveness of the IR-S human breast cancer cell lines MDA-MB-231, Hs578T, MCF-7 and the mouse mammary tumor cell line 4T1." (PMID 33110168, 2020). "The association of lysosomes to kinesins is mediated by Arl8b and the BORC complex, and a high expression of both Arl8b and the BORC-subunit proteins, BLOC1S2 and BORCS5, are correlated to a poor prognosis and an increased invasive capacity in breast cancer and prostate cancer, respectively." (PMID 38474423, 2024). "Notably, high expression of ARL8B and BORC-subunit genes is significantly correlated with poor prognosis in breast cancer patients." (PMID 33110168, 2020).
prostate carcinoma (5 papers, 2015 to 2024). A carcinoma that arises from epithelial cells of the prostate gland. "In fact, upon loss of Arl8b, prostate cancer cells were absolutely unable to grow as xenograft tumors." (PMID 27105540, 2016). "The dysregulation of ARL8B vesicular trafficking machinery has been implicated in therapeutic resistance and cancer pathogenesis, and is associated with an increased risk of disease recurrence in patients with prostate cancer." (PMID 39217195, 2024). "Most notably, we found Arl8b is essential for in vivo xenograft tumor growth of prostate cancer cells." (PMID 27105540, 2016). "To assess this possibility, we collected whole cell lysates from DU145 and PPC1 cells expressing NT or Arl8b shRNA and probed for prostate cancer stem cell markers, CD44 and ALDH1A1, by immunoblot." (PMID 27105540, 2016). "We have made several observations indicating a metabolic consequence of Arl8b depletion on prostate cancer growth." (PMID 27105540, 2016). "Strikingly, we found that depletion of Arl8b abolishes the ability of prostate cancer cells to establish subcutaneous xenografts in mice." (PMID 27105540, 2016). "ADP-ribosylation factor-like 8b (ARL8B), among the enriched proteins in prostate cancer patients urinary exosomes, has been associated with the LAMTOR complex too, in particular with LAMTOR2/3 and its role in cell migration." (PMID 26196085, 2015). "Overall, these data suggest Arl8b is a potential target to prevent prostate cancer progression." (PMID 27105540, 2016). "Depletion of Arl8b results in juxtanuclear lysosome aggregation, and this effect corresponds with both diminished invasive growth and proteolytic extracellular matrix degradation in a three-dimensional model of prostate cancer." (PMID 27105540, 2016). "In this report we demonstrated that Arl8b, through its interaction with kinesin Kif5b, is required for this response in multiple cell lines and that by depleting Arl8b, protease secretion is reduced and prostate cancer invasive growth within a 3D ECM model is greatly impaired." (PMID 27105540, 2016). "Most strikingly, we found that prostate cancer cells depleted of Arl8b did not form subcutaneous xenograft tumors." (PMID 27105540, 2016).
amyloid (2 papers, 2022 to 2023). "We found a strong correlation between Arl8b- and 6E10-stained structures in hippocampal tissues of all three ages, suggesting that the time-dependent formation of amyloid plaques determines the size of the adjacent Arl8b-positive lysosomal structures in 5xFAD brains." (PMID 37468900, 2023). "Instead, ARL8B was often observed in the regions of amyloid plaques that were not brightly stained for Aβ." (PMID 35418158, 2022).
lysosomal disorders (2 papers, 2024 to 2026). "Deficiency of TPP1 and PPT1 have been linked to the neurodegenerative lysosomal storage disease neuronal ceroid lipofuscinosis (NCL), and ARL8B also has been linked to a lysosomal storage disorder, Niemann-Pick disease type C." (PMID 39070643, 2024). "These viruses use the Arl8b-dependent lysosomal exocytic pathway for egress, potentially contributing to lysosomal disorders." (PMID 41288096, 2026).
Salmonella Infections (2 papers, 2023). Infections with bacteria of the genus SALMONELLA. "To test functionally the impact of RUFY3 on EL function, we performed Salmonella infection, since ARL8b/PLEKHM2/HOPS- and Rab7/PLEKHM1-dependent EL mobilizations are particularly important for the maturation of Salmonella-containing vacuoles (SCV) and bacterial replication in macrophages." (PMID 37463962, 2023). "Contrary to our expectation, Salmonella infection was also enriched in clusters 1 and 3, and thus, we reviewed the DEGs and found that only six DEGs, such as AHNAK, MAP2K1, MAPK10, ARL8B, IL6, and PFN2, were enriched after S. enterica BNCC186354 infection, but only ARL8B and PFN2 were downregulated." (PMID 36980306, 2023).
Cognitive impairment (1 paper, 2023). Abnormal cognition is characterized by deficits in thinking, reasoning, or remembering. "Interestingly, we also observed a moderate positive correlation between Arl8b and p-tau protein levels in CSF samples, suggesting that an increase of Arl8b is also associated with cognitive impairment in AD patients." (PMID 37468900, 2023).
COVID-19 (1 paper, 2023). A disease caused by infection with severe acute respiratory syndrome coronavirus 2. "This work highlights that targeting regulators of lysosomal trafficking and biogenesis, such as Arl8b and Rab7, may be the potential strategies to stop transmission of the virus that causes βCoVs disease, for instance, COVID-19." (PMID 38009916, 2023).
lymph node metastasis (1 paper, 2020). "The ARL8B/BLOC1S2-high group was also found to be associated with an increased rate of lymph node metastasis." (PMID 33110168, 2020).
Niemann-Pick disease (1 paper, 2023). A group of inherited, severe metabolic disorders in which sphingomyelin accumulates in lysosomes in cells. "This view is also supported by a recent study indicating that elevated Arl8b expression rescues lysosome transport and thereby reduces axonal autophagic stress and neuron death in Niemann-Pick disease." (PMID 37468900, 2023).
osteopetrosis (1 paper, 2017). Osteopetrosis, also known as marble bone disease, is a descriptive term that refers to a group of rare, heritable disorders of the skeleton characterized by increased bone density on radiographs. "Arl8b and PLEKHM1 interaction might have implications in the human disease osteopetrosis, a genetic disorder caused by loss-of-function mutations in PLEKHM1 that disrupt osteoclast function in bone resorption, resulting in disorganized bone structure." (PMID 28325809, 2017).
ovarian carcinoma (1 paper, 2016). A malignant neoplasm originating from the surface ovarian epithelium. "We also identified several novel hub genes that were previously unreported in ovarian cancer, such as BCL2-associated transcription factor 1 (BCLAF1), ADP-ribosylation factor-like 8B (ARL8B), and SEC31 homolog A (S. cerevisiae) (SEC31A)." (PMID 26972162, 2016).
prostate tumor (1 paper, 2016). "We found that Arl8b is required for invasion and protease secretion in 3D culture and report that Arl8b is required for prostate tumor growth in a xenograft mouse model." (PMID 27105540, 2016).
virus infection (1 paper, 2017). "We next investigated the role of Arl8b in TLR7 responses toinfluenza virus infection of pDCs." (PMID 29150602, 2017).
cancer (7 papers, 2016 to 2024). A tumor composed of atypical neoplastic, often pleomorphic cells that invade other tissues. "Here, we show that invasiveness in radiation-surviving cancer cells is associated with alterations in lysosomal exocytosis caused by the enhanced activation of Arl8b, a small GTPase that regulates lysosomal trafficking." (PMID 33110168, 2020). "Arl8b can be recruited to lysosomes in response to ErbB2 signaling, supporting a mechanism for lysosome redistribution in response to cancer-associated extracellular stimuli." (PMID 27105540, 2016). "Furthermore, recent lines of evidence show that the mechanism by which some cancer cells become resistant to radiation is associated with lysosomal exocytosis, which is enhanced by the activity of Arl8b." (PMID 34977038, 2021). "ARL8B is a small GTPase that plays a critical role in autophagy and the secretion of MMPs that can facilitate cancer progression." (PMID 39217195, 2024). "In both LNCaP and PC-3 cancer cells, increased ARL8B expression induced a notable perinuclear-to-peripheral distribution shift in lysosomal positioning (P = 0.0159, P = 0.018 respectively), a phenomenon not observed in non-malignant PNT1a cells (P = 0.112)." (PMID 39217195, 2024). "We next sought to identify the regulatory factors of Arl8b at work in highly invasive cancer cells that survive IR." (PMID 33110168, 2020). "In this study, we show that Arl8b activation is increased in highly invasive cancer cells that survive IR and that this process is regulated by BORC." (PMID 33110168, 2020). "Here, we found that BORC-subunits are required for Arl8b-mediated lysosomal exocytosis and invasion in IR-S cancer cells." (PMID 33110168, 2020). "Taken together, and consistent with the data obtained in vitro, these in vivo results indicate that Arl8b, a regulator of lysosomal exocytosis, is essential for the increased tumor growth and metastasis of highly invasive cancer cells that survive IR." (PMID 33110168, 2020). "Arl8b-HA-transfected MDA-MB-231 cells were used to measure the distribution of Arl8b in cancer cells." (PMID 33110168, 2020). "Future work will further clarify the role of Arl8b-dependent lysosome function in vivo at different stages of cancer progression." (PMID 27105540, 2016). "In conclusion, we have identified two mechanisms by which Arl8b regulates cancer progression: 1) through lysosome positioning and protease release leading to an invasive phenotype and 2) through control of lipid metabolism to support cellular proliferation." (PMID 27105540, 2016). "The results presented herein indicate two critical roles for Arl8b in cancer progression through control of lysosome mobility or fusion." (PMID 27105540, 2016). "These novel roles highlight that Arl8b is a potential target for the development of novel anti-cancer therapeutics." (PMID 27105540, 2016). "Regardless, we have provided evidence of two mechanisms for Arl8b involvement in cancer progression." (PMID 27105540, 2016). "An increase of lysosomal exocytosis has been described in cancer cells overproducing Arl8b, hinting that this process may also be enhanced in neuronal cells, which contain lysosome-like organelles with high local concentrations of Arl8b." (PMID 37468900, 2023). "Due to the significant effect of Arl8b on highly invasive cancer cells that survive IR, we sought to validate whether Arl8b is required for invasive tumor growth and metastasis in a mouse model." (PMID 33110168, 2020). "Arl8b-mediated lysosome positioning at the cell periphery regulates diverse cellular processes, including amino acid sensing, antigen presentation, cell migration, and cancer metastasis." (PMID 28325809, 2017). "Due to the known roles of integrins and Rho family GTPases in cancer cell invasion and the possible connection with lysosome mobility, we assayed for changes in expression and/or activity of these proteins in response to Arl8b KD." (PMID 27105540, 2016).
cancer (continued). "To confirm the activation of endogenous Arl8b in invasive cancer cells, we transfected V5-SKIP and Arl8b-HA into MDA-MB-231 cells." (PMID 33110168, 2020). "High levels of Arl8b and BORC subunit genes is indeed correlated with a poor prognosis in breast cancer, and knockdown of these genes decreases the survival and invasiveness of cancer cells." (PMID 34977038, 2021). "Collectively, these results support the hypothesis that Arl8b plays a key role in lysosomal trafficking to the periphery of IR-S cells, which in turn results in increased ECM degradation and cancer cell invasion." (PMID 33110168, 2020). "Others’ and our data suggest that Arl8b-regulated lysosomal exocytosis is essential for the stimulation-dependent invasiveness, but not the basal invasiveness, of cancer cells." (PMID 33110168, 2020). "To determine whether Arl8b affects the long-term survival of cancer cells with or without IR, we performed a clonogenic cell survival assay." (PMID 33110168, 2020).
infection (6 papers, 2011 to 2023). The state of being infected such as from the introduction of a foreign agent such as serum, vaccine, antigenic substance or organism. "Taken together, these results confirmed that PHEV utilizes Arl8b-dependent lysosomal exocytic pathways for egress during infection." (PMID 38009916, 2023). "Arl8b-silenced cells showed at least twice as many viable bacteria as control cells at 30 min and 90 min after infection, indicating a defect in microbial killing." (PMID 21802320, 2011). "E. coli GFP were opsonized through binding of mouse serum, added to Arl8b-silenced or control RAW cells plated on glass coverslips, and infection synchronized by centrifugation of the bacteria onto the cells." (PMID 21802320, 2011). "To directly measure intracellular killing of the microbe, we infected Arl8b-silenced or control cells with E. coli GFP as above, and at various times after infection viable E. coli were recovered through gentle detergent cell lysis." (PMID 21802320, 2011). "To test whether BORC-related lysosome trafficking components mediate BCV trafficking during infection, we analyzed the dynamics of the interaction of BCVs with LAMTOR1 (a central component of mTORC1), the small GTPase ARL8b, and kinesin KIF1b and KIF5b proteins during infection." (PMID 35587649, 2022). "It is interesting to speculate that Arl8b- but not Rab7-positive lysosomes act as source of membrane for SCV biogenesis and SIF formation during later time points of infection." (PMID 29084291, 2017).
tumor (3 papers, 2016 to 2022). "Metabolic defects in the proliferation of cells with low Arl8b expression inhibit tumor growth initiation in vivo." (PMID 35747825, 2022). "In vivo, suppression of Arl8b levels inhibited radiation-induced invasive tumor growth and distant metastasis." (PMID 35747825, 2022). "In vivo experiments show that ablation of Arl8b decreases IR-induced invasive tumor growth and distant metastasis." (PMID 33110168, 2020). "We then validated that Arl8b is involved in the distal metastasis of IR-S tumor cells using in vivo imaging and hematoxylin and eosin (H&E) staining of lung tissues." (PMID 33110168, 2020). "Due to the strong effect of Arl8b silencing on tumor cell invasion in 3D Matrigel, we sought to determine the necessity of Arl8b for tumor progression in vivo." (PMID 27105540, 2016). "The results from this initial experiment showed a striking difference in tumor growth between NT and Arl8b KD cells." (PMID 27105540, 2016). "Therefore, Arl8b regulates spatial distribution of lysosomes and protease release through lysosomal localization, leading to elevated tumor cell invasiveness." (PMID 35747825, 2022). "However, shRNA-mediated knockdown of Arl8b in 4T1-Luc cells effectively suppressed the IR-induced increase in invasive tumor growth in the mice." (PMID 33110168, 2020). "Finally, Arl8b silencing suppressed the increased tumor growth and distant metastasis of IR-S cells in a mouse xenograft model." (PMID 33110168, 2020). "However, it is possible that the proteolytic role of Arl8b is required for the initial establishment of a tumor bed in which to grow through ECM remodeling." (PMID 27105540, 2016). "We present evidence that Arl8b facilitates lipid hydrolysis to maintain efficient metabolism for a proliferative capacity in low nutrient environments, suggesting a likely explanation for the complete inability of Arl8b-depleted tumor cells to grow in vivo." (PMID 27105540, 2016). "Given the inability of Arl8b depleted cells to initiate tumor growth in vivo, we sought to determine whether Arl8b knockdown resulted in a depleted stem cell population." (PMID 27105540, 2016). "Herein, we analyzed whether Arl8b plays a role in tumor progression." (PMID 27105540, 2016). "1×106 NT or Arl8b KD PPC1 cells were injected subcutaneously into the hind flank of SCID/bg male mice and tumor growth was measured twice-weekly using a caliper." (PMID 27105540, 2016). "Recent reports suggest that Arl8b regulates cell motility and cell spreading; however, Arl8b has not yet been investigated in the context of tumor growth and invasion." (PMID 27105540, 2016). "The lack of tumor growth from Arl8b depleted cells indicates an essential role for Arl8b in tumor seeding and growth initiation within an in vivo environment." (PMID 27105540, 2016). "Representative images of mice clearly show the substantial growth of NT cell xenografts and the complete absence of tumor formation from Arl8b shRNA expressing cells." (PMID 27105540, 2016). "However, the role of Arl8b in tumor cell invasion and protease secretion has not been previously investigated." (PMID 27105540, 2016).
ARL8B also shares sentences with these, for which no sentence is quoted: Alzheimer disease (1 paper); Bacterial infection (1); genetic disorder (1); neuronal ceroid lipofuscinosis (1); Niemann-Pick disease type C (1); prion disease (1); tuberculosis (1).